FAP (fibroblast activation protein alpha)
Diseases named in the same sentence as FAP in open-access papers (continued):
Sharing a sentence is not in itself a finding about the gene and the disease.
cervical cancer (17 papers, 2008 to 2026). A primary or metastatic malignant neoplasm involving the cervix. "Prior nuclear imaging studies have shown that almost all cancer-associated fibroblasts within uterine cervix cancer tumors express the radiopharmaceutical target FAP when assessed by radiotracer uptake criteria." (PMID 42306799, 2026). "In conclusion, our findings indicate that the FAP+ CAF population is linked to increased tumor progression in cervical cancer, underscoring the pivotal role of the FAP protein in the processes of proliferation and invasion." (PMID 38606999, 2024). "FAP is a cell-surface protease expressed in reactive stromal fibroblasts of epithelial cancers, and is associated with invasion and metastasis in gastric, colorectal and cervical carcinoma." (PMID 18544165, 2008). "In advanced stages of cervical cancer, we found that there is an overexpression of FAP and MMP9 with a positive trend." (PMID 38606999, 2024). "Among these, adenocarcinoma, cervical cancer, and squamous cell carcinoma exhibited improved outcomes with heightened FAP expression." (PMID 38558814, 2024). "FAP-α immunoreactivity was observed in some microinvasive and all invasive cervical carcinomas with various degrees of FAP-α -positive stromal cells." (PMID 24885257, 2014). "In summary, FAP has a crucial role in the activation of CAFs during cervical cancer progression." (PMID 38606999, 2024). "In an early-phase human trial involving FAP-IL-2v in combination with the anti-PD-L1 drug atezolizumab for patients with metastatic or recurrent cervical cancer, a favorable safety profile and significant anti-tumor activity were observed compared to approved PD-1 inhibitors." (PMID 38558814, 2024). "We found that CAF markers, such as fibroblast activation protein (FAP), ACTA2 (α-SMA), and beta-type platelet-derived growth factor receptor (PDGFRB) were associated with the infiltration of macrophages in cervical cancer in the Tumor Immune Estimation Resource (TIMER) database." (PMID 36900416, 2023). "The dosimetric results and findings described in the T/B ratios of the primary and metastatic lesions suggest that [99mTc]Tc-iFAP imaging is a safe and potentially useful tool to assess FAP expression in the tumor microenvironment of various solid tumors, such as breast, lung, and cervical cancer." (PMID 35631416, 2022). "Our results demonstrate that supernatants from cervical cancer cell lines (HeLa and SiHa) can promote the differentiation of MSCs into a CAF phenotype by inducing the overexpression of proteins such as αSMA and FAP." (PMID 38606999, 2024). "For these reasons, this study evaluated the effect of supernatants from cervical cancer cell lines (HeLa and SiHa) in the expression of vimentin, S100A4, αSMA, FAP, and MMP9 markers in an in vitro MSC-CAF model." (PMID 38606999, 2024). "This study aimed to evaluate the protein expression of vimentin, S100A4, αSMA, FAP, and MMP9 in mesenchymal stem cells (MSC)-CAF cells, as well as in cervical cancer samples." (PMID 38606999, 2024). "In addition, we investigated the protein levels of vimentin, S100A4, αSMA, FAP, MMP9, and Ki67 in different stages of cervical cancer." (PMID 38606999, 2024). "When investigating whether cervical cancer cells conditioned media lead to a heterogeneous MSC activation phenotype, we found a high fluorescence intensity of αSMA and FAP indicating a differentiation towards an MSC-CAF phenotype." (PMID 38606999, 2024). "To determine whether cervical cancer cells conditioned media (SiHa and HeLa) can promote differentiation towards an MSC-CAF phenotype we evaluated vimentin, S100A4, αSMA, FAP, and MMP9 expression by immunofluorescence." (PMID 38606999, 2024).
fibrosarcoma (17 papers, 2016 to 2025). A malignant mesenchymal fibroblastic neoplasm affecting the soft tissue and bone. "[68Ga]Ga- and [225Ac]Ac-FAPI-46 were tested in subcutaneous FAP+ FSA fibrosarcoma bearing C3H/Sed/Kam mice." (PMID 39008063, 2024). "FAP positivity was previously documented in human fibrosarcoma (5/5), MFS (4/4), leiomyosarcoma (8/10), liposarcoma (3/4), and undifferentiated sarcoma (2/3) cell lines." (PMID 37727209, 2023). "At the investigated time point, the stable FAP expressing fibrosarcoma model is still strongly fluorescent as compared to the other organs, irrespective of the probe applied." (PMID 33076292, 2020). "In contrast, FAP-IL and LipQ accumulated slowly and persistently in both tumor models, whereby higher fluorescence signals were seen in the fibrosarcoma model." (PMID 32316521, 2020). "The data presented herein comprises tabulated observations and tumor volumes of mice co-implanted with wildtype and FAP-expressing fibrosarcoma cells, as well as histological sections of the excised tumors and lungs." (PMID 27642620, 2016). "For instance, in a murine fibrosarcoma model (MCA205) stably expressing FAP, treatment with 60 MBq of the radiopharmaceutical 177Lu-FAP-2287 in combination with an anti-PD-1 immune checkpoint inhibitor resulted in a greater infiltration of CD45+ leukocytes compared to monotherapy." (PMID 40725216, 2025). "The MCA205 fibrosarcoma cell line was engineered to express murine FAP, after initial screening of multiple syngeneic and GEMM tumors showed minimal to no FAP staining in contrast to patient tumors that are commonly infiltrated with significant FAP-positive CAFs." (PMID 37086273, 2023). "When combining αFAP–TNFL fusion proteins with αEpCAM–αCD3, we observed a significant augmentation of cytotoxicity for all four constructs, suggesting that they were able to deliver co-stimulation for cytotoxic effector functions by engaging the FAP antigen expressed on admixed fibrosarcoma cells." (PMID 34484225, 2021). "Although [125I]I-FAPI-01 exhibited rapid internalization in both murine FAP-transfected human embryonic kidney (HEK) cells and human FAP-transfected fibrosarcoma HT-1080 cells in vitro, time-dependent efflux and enzymatic deiodination of [125I]I-FAPI-01 eliminated its further preclinical evaluation." (PMID 34681246, 2021). "The data additionally shows that FAP, when overexpressed on fibrosarcoma cells induces their invasion and formation of spontaneous metastases in multiple organs, particularly after subcutaneous co-implantation of the FAP-expressing and wildtype fibrosarcoma." (PMID 27642620, 2016). "In the current study, we use a syngeneic model of murine fibrosarcoma (FSA), which expresses FAP, is radiosensitive and amenable to immunotherapeutic perturbation." (PMID 39008063, 2024). "Herein, we demonstrate that combined therapies using radiolabeled FAP-targeting agent 177Lu-FAP-2287, a murine surrogate of 177Lu-FAP-2286, together with PD-1 checkpoint blockade induce tumor inhibition in a FAP expressing MCA205 fibrosarcoma tumor model." (PMID 37086273, 2023). "In mice bearing the human fibrosarcoma, HT1080-hFAP tumors, the mEdg’scFv based liposomes (Bi-FAP/mEnd-IL and mEnd-IL) showed a rapid accumulation in the tumors within the initial minutes post application and a strong background fluorescence of the skin and organs of the mice (Bis-IL and mEnd-IL)." (PMID 32316521, 2020).
lung adenocarcinoma (17 papers, 2016 to 2026). A carcinoma that arises from the lung and is characterized by the presence of malignant glandular epithelial cells. "Previous work has linked stromal FAP to immune cell infiltration, including CD8+ T cells and CD163+ macrophages, in MRI‐visible prostate tumours, lung adenocarcinoma, and in clear cell renal cell carcinoma." (PMID 41410015, 2026). "We queried FAP mRNA expression using the TCGA database and found that FAP was upregulated in lung adenocarcinoma (LUAD) and lung squamous cell carcinoma (LUSC) compared with normal lung tissues." (PMID 38459511, 2024). "IHC results further revealed that the tumor developed in the A549-FAP lung adenocarcinoma model had a high expression of FAP." (PMID 35071007, 2021). "(n=89), and multiplexed immunohistochemistry (IHC) staining of these two cases to decipher the poor prognosis dependent on the immunosuppressive barrier formed by FAP+ fibroblasts and SPP1+ macrophages in the SMARCA2-deficient while SMARCA4-preserved poorly differentiated lung adenocarcinoma (LUAD)." (PMID 40453096, 2025). "A significant increase in the gene expression of multiple CAF markers associated with different subsets of CAFs, including fibroblast activation protein-alpha (FAP-α) expressing CAFs, was observed in invasive lung adenocarcinoma compared to noninvasive lung adenocarcinoma." (PMID 39058055, 2024). "FAP expression was positively linked to MSI in colon adenocarcinoma and negatively related to cholangiocarcinoma, lung adenocarcinoma, uveal melanoma, STAD, lung squamous cell carcinoma (LUSC), skin cutaneous melanoma, and head and neck squamous cell carcinoma (HNSC)." (PMID 35359436, 2022). "In early-stage lung adenocarcinoma (stage IA), 18F-FAPI-04 PET/CT demonstrated higher SUVmax and tumor-to-background ratios than FDG, with tracer uptake correlating with FAP expression on immunohistochemistry." (PMID 41441395, 2025). "In the present study, we were the first to report a spatial “exclusion phenomenon” between FAP+ CAFs and CD8+ T cells in lung adenocarcinoma (LUAD)." (PMID 40855046, 2025). "Our investigation revealed that COL1A1, COL1A2, FAP, and PDGFRA are effective markers for characterizing CAF subgroups in most lung adenocarcinoma datasets." (PMID 39034310, 2024). "As to FAP, although it could indicate survival expectance in overall survival, and the progression-free of stage I lung adenocarcinoma, but FAP did not define any difference in progression-free of other groups of lung adenocarcinoma." (PMID 39034310, 2024). "Notably, although FAP expression was reported as an independent biomarker of a poor prognosis for lung adenocarcinoma (LUAD), none of the previous studies have confirmed the possibility that FAP is linked to the outcome of PD-1 blockade therapy and immune infiltrates in advanced NSCLC." (PMID 35951090, 2023). "However, CAR-T cells against LSCC have never been reported although CAR T cells that target FAP, EphA2 and EGFR have been developed for the treatment of lung adenocarcinoma." (PMID 26684028, 2016).
metastatic tumors (17 papers, 2016 to 2026). "FAP-2286 is another study for diagnostic peptidomimetics, which binds to fibroblast activation protein (FAP) to evaluate the uptake, retention, and ability to detect metastatic disease of radiotracers in a variety of solid tumors." (PMID 36476230, 2022). "For example, a study assessing an early experience with 68Ga-FAP-2286 PET, a novel fibroblast activation protein (FAP) binder, found that it was highly sensitive in patients with localized and metastatic disease." (PMID 41021053, 2025). "Taken together, FAP+CAFs are populated in metastatic tumors with inferior clinical outcomes in NSCLC patients." (PMID 38459511, 2024). "Then, we determined the presence of parental fibroblasts in the orthotopic PDX and in metastatic tumors by immunoblotting with anti-human FAP." (PMID 35837106, 2022). "Nevertheless, recent studies confirm that FAP imaging is comparable or even superior to FDG imaging in lung metastatic tumor spread." (PMID 34050777, 2021). "Histologically, FAP expression was evaluated in the fibroblasts of the tumor stroma in both primary and metastatic tumors." (PMID 28033421, 2016). "According to the relevance of FAP as prognostic and predictive biomarker, FAP-targeted molecules such as small molecule inhibitors (FAPIs) are of interest as radioactive theranostic drugs used to diagnose and treat the primary and any metastatic tumors." (PMID 35471681, 2022). "High FAP expression has been proposed as a biomarker for disease progression in metastatic tumor." (PMID 36401232, 2022). "In contrast, high FAP expression in matrix components of gastrointestinal tumors and metastatic tumors, rapid clearance by the kidney, less physiological uptake in normal organs, and high tumor-to-background ratio render [68Ga]Ga-FAPI-04 more advantageous for abdominal and pelvic imaging." (PMID 35847877, 2022). "FAP is not found in normal adult tissues and its expression is largely associated to the stroma of primary and metastatic tumors." (PMID 28033421, 2016). "Further studies will be necessary to contribute to a more detailed understanding of the role of FAP in cross-communications between cells of TME from primary and metastatic tumors." (PMID 32428869, 2020).
osteoarthritis (17 papers, 2006 to 2025). A noninflammatory degenerative joint disease occurring chiefly in older persons, characterized by degeneration of the articular cartilage, hypertrophy of bone at the margins and changes in the synovial membrane. "Sublining CD90+ FAP+ synovial fibroblasts, the only subtype reported as pathogenic, which is specifically increased in RA compared with osteoarthritis and CD90+ activated endothelium show high GM-CSF expression." (PMID 33679701, 2020). "While RANKL is a crucial osteoclastogenic cytokine in both membrane-bound and soluble forms, FAP has recently been identified to be a regulator of osteogenesis and bone formation, as well as a pathological factor in osteoarthritis." (PMID 38346941, 2024). "Expression of FAP in synovial tissues and fibroblasts from patients with osteoarthritis (OA) and RA as well as from wild-type and arthritic mice was evaluated by immunohistochemistry, fluorescence microscopy and polymerase chain reaction (PCR)." (PMID 25600705, 2015). "Both podoplanin and FAP are known to be involved in EMT and are reported to be highly expressed in cells of the intimal lining layer in RA, with little expression in osteoarthritis synovium." (PMID 28793332, 2017).
pancreatic adenocarcinoma (17 papers, 2011 to 2025). "In invasive ductal carcinoma of the breast, FAP+CAFs have been associated with longer survival, while in pancreatic adenocarcinoma and rectum they are found to be associated with worse clinical outcome." (PMID 35222418, 2022). "In this article, we aim to systematically review the recent advances in research on FAP in pancreatic adenocarcinoma, including its utility as a diagnostic marker, therapeutic potential, and correlation with prognosis." (PMID 36263225, 2022). "Moreover, human pancreatic adenocarcinoma-associated fibroblasts produced ECMs oriented in parallel patterns, which are similar to the patterns formed by FAP+ matrices." (PMID 21668992, 2011). "Interestingly, our human pancreatic adenocarcinoma-associated fibroblast ECMs, as well as our FAP+ 3D matrices in vitro, also presented the parallel organized patterns highlighted by the two studies above." (PMID 21668992, 2011). "FAP showed a similar effect on the prognosis of THCA and UVM as FBLN1, and was also associated with favorable prognosis of pancreatic adenocarcinoma (PAAD)." (PMID 40433364, 2025). "In murine models of pancreatic adenocarcinoma, inhibition of FAP proteolytic activity resulted in decreased macrophage recruitment, and genetic knockout of FAP enhanced T cell infiltration and cytotoxicity." (PMID 35222418, 2022). "Actually, the clinical trials of FAP-targeting radiotherapy are ongoing in patients with different types of cancer, including nasopharyngeal carcinoma and pancreatic adenocarcinoma." (PMID 35565232, 2022). "Pre-clinical trials targeting CAFs indicated that targeting a subpopulation of FAP+ CAFs was beneficial in transplantable models of Lewis lung carcinoma and pancreatic adenocarcinomas." (PMID 31428105, 2019). "Importantly, we showed that FAP+ matrices contain parallel fiber organization features that are reminiscent of tumor-associated ECMs of pancreatic desmoplastic tissues associated with pancreatic adenocarcinoma looking at human normal and tumor ECMs both in vivo and in vitro." (PMID 21668992, 2011). "The first-in-human study of [177Lu]Lu-FAP-2286 for peptide-targeted radionuclide therapy (PTRT) was carried out on 11 patients with advanced adenocarcinomas of the pancreas, breast, rectum, or ovary with prior confirmation of uptake on [68Ga]Ga-FAP-2286 or [68Ga]Ga-FAPI-04 PET/CT." (PMID 41049848, 2025). "Notably, FAP expression levels were highest in pancreatic adenocarcinoma (PAAD) and lowest in acute myeloid leukemia (LAML)." (PMID 37490719, 2023). "FAP was not only consistently expressed in the peritumoral and intratumoral stromal compartment of carcinomas but also in some types of tumor cells, such as pancreatic adenocarcinoma, osteosarcoma, esophageal adenocarcinoma and epithelial ovarian carcinoma." (PMID 25775399, 2015). "Activated pancreatic stellate cells (i.e., myofibroblastic cells) express α-SMA and FAP (among other markers) and correspond to the cells believed to be responsible for the fibrosis in chronic pancreatitis and the desmoplastic reactions in pancreatic adenocarcinomas." (PMID 21668992, 2011). "In a mouse model of pancreatic adenocarcinoma (PAAD), Feig C and colleagues found that the depletion of FAP positive cells contributed to improved anti-CTLA-4 or anti-PD-L1 immunotherapy efficacy, revealing the immune suppressive effect of FAP in cancers." (PMID 37325617, 2023).
malignant pleural mesothelioma (16 papers, 2012 to 2025). A malignant neoplasm that arises from mesothelial cells in the pleura and shows a diffuse growth pattern. "A phase I clinical trial of CAR‐T cell therapy targeting FAP was conducted in patients with malignant pleural mesothelioma." (PMID 40656546, 2025). "A phase I clinical trial using FAP-CAR-T-cells on patients with malignant pleural mesothelioma demonstrated that FAP-CAR-T-cell was well tolerated, and persistence of CAR T-cells was detected in the periphery (NCT01722149)." (PMID 37035187, 2023). "with FAP-specific CAR-T cells combined to anti-PD-1 mAbs against a malignant pleural mesothelioma cell line." (PMID 35211124, 2022). "The first one is a phase I clinical trial (NCT01722149) using CD3ζ/CD28-based FAP-specific CAR-T cells in three patients with malignant pleural mesothelioma." (PMID 35211124, 2022). "Another phase 1 study is analyzing the effect of re-directed FAP-specific T-cells in FAP-positive malignant pleural mesothelioma (NCT01722149)." (PMID 30781344, 2019). "The data encouraged the research team from the University of Zurich Switzerland to open a new clinical phase I trial (NCT01722149) to study the effect of FAP-specific CD8 positive T cells in malignant pleural mesothelioma patients." (PMID 26798356, 2016). "FAPα-specific redirected T cells for the treatment of FAPα-positive malignant pleural mesothelioma are currently subject to clinical trials." (PMID 25593080, 2015). "We analyzed the three distinct histologic subtypes of malignant pleural mesothelioma from a total of 18 patient biopsies for FAP expression." (PMID 23937772, 2013). "This is a phase I trial for patients with malignant pleural mesothelioma with pleural effusion testing the safety of a fixed single dose of 1x106 adoptively transferred FAP-specific re-directed T cells given directly in the pleural effusion." (PMID 23259649, 2012). "Despite poor success in cancer therapy, a recent anti-FAP preclinical study of malignant pleural mesothelioma, an incurable disease resulting from exposure to asbestos, suggested lysis of FAP positive cells, inhibited tumor growth, and significantly prolonged the survival of the mice." (PMID 26798356, 2016). "Since our first planned clinical protocol (manuscript is published: Petrausch U, Schuberth PC, Hagedorn C, Soltermann A, Tomaszek S, Stahel R, Weder W, Renner C: Re-directed T cells for the treatment of fibroblast activation protein (FAP)-positive malignant pleural mesothelioma (FAPME-1)." (PMID 23937772, 2013).